ENSG00000270442 (peptidylprolyl isomerase G (cyclophilin G) (PPIG) pseudogene)
Synonyms: PPIGP1
Gene: Processed pseudogene on chromosome 5 (155,491,336 to 155,493,598, forward strand). Ensembl gene ENSG00000270442.
Diseases named in the same sentence as ENSG00000270442 in open-access papers:
ENSG00000270442 is named in the same sentence as 1 disease in open-access papers, as found by Europe PMC text mining. Sharing a sentence is not in itself a finding about the gene and the disease.
ENSG00000270442 shares sentences with these, for which no sentence is quoted: cervical cancer (1 paper).